INS (insulin)
Diseases named in the same sentence as INS in open-access papers (continued):
Sharing a sentence is not in itself a finding about the gene and the disease.
Hyperglycemia (continued). "In rodent studies, oleanolic acid also attenuated fructose-induced hyperglycemia by regulating enzymes involved in carbohydrate digestion, insulin secretion and insulin signaling." (PMID 39063310, 2024). "Other factors including hyperglycemia, increased insulin demand, and oxidative or endoplasmic reticulum stress have been proposed as inhibitors of insulin secretion." (PMID 38875221, 2024). "The complex interplay between these two disease processes presented with grossly elevated baseline insulin requirements and refractory intraoperative hyperglycemia." (PMID 39347258, 2024). "Impaired insulin secretion by pancreatic β-cells is a core pathomechanism of T2DM, where disease progression hampers insulin secretion’s ability to maintain glucose homeostasis, leading to hyperglycemia." (PMID 38659573, 2024). "Counter-regulatory hormones exert their effects by modulating gene expression and inhibiting specific processes to stimulate the production of new glucose in the liver (gluconeogenesis) and reduce the effectiveness of insulin, resulting in hyperglycemia." (PMID 39682557, 2024). "Symptoms of IAS are recurrent fasting hypoglycaemia, postprandial hyperglycaemia, and post-meal hypoglycaemia which is due to the presence of increased insulin levels and insulin autoantibodies." (PMID 38428138, 2024). "This is due to fewer complications related to DKA or hyperglycemia and reduced need for exogenous insulin treatment." (PMID 39070316, 2024). "They concluded that insulin therapy must be taken into consideration when hyperglycemia cannot be properly controlled." (PMID 38612849, 2024). "That is, in the presence of an acute event—such as critical illness—people with preexisting, subclinical impairment of β-cell function cannot cope with the sudden increase in insulin demand and develop hyperglycemia." (PMID 37934800, 2024). "The initial stage in the development of hyperglycemia involves a delay in first-phase insulin secretion, followed by a decrease in total insulin secretion." (PMID 38541202, 2024). "GH assesses serum glucose levels, and hyperglycemia induces insulin release, which ameliorates vascular endothelial cell injury." (PMID 38553747, 2024). "The plant extracts described in this section have antidiabetic effects because they improve glycemic control and lipid profile, postprandial hyperglycemia, insulin resistance, inflammatory cytokines, and oxidative stress in diabetic models." (PMID 39065815, 2024). "While he had never experienced diabetic ketoacidosis (DKA), he had a history of occasional hyperglycemia and episodes of hypoglycemia, often due to irregular insulin dosing or missed meals." (PMID 39759658, 2024). "In KKAy mice, APS improved hyperglycemia and systemic insulin sensitivity and reduced hepatic triglyceride and free fatty acid content." (PMID 38659573, 2024). "Hyperglycemia is a key feature of T1DM due to the cessation of endogenous insulin secretion, while exogenous insulin administration can lead to hypoglycemia." (PMID 39203886, 2024). "Our results suggest that imeglimin mitigates the accumulation of dysfunctional mitochondria in β-cells from db/db mice, leading to an increase in the amount of secreted insulin, suppression of apoptotic β-cell death and amelioration of hyperglycemia." (PMID 38485716, 2024). "GLP-1RAs achieve glycemic control through mechanisms such as boosting insulin secretion induced by hyperglycemia, decreasing glucagon secretion during hyperglycemia, slowing gastric emptying, and preventing significant increases in postprandial glucose." (PMID 39184671, 2024). "This destruction leads to chronic hyperglycemia, necessitating lifelong insulin therapy to manage blood glucose levels." (PMID 39411715, 2024). "Metabolically healthy mice exhibit rapid metabolic shifts on this timescale, including fasting and post-absorptive (2-hr fast) hyperglycemia and an elevated insulin response to glucose." (PMID 37066282, 2024).
Hyperglycemia (continued). "These systems, however, allow parents to become more confident, thanks to the automatic insulin delivery suspension, leading to a reduction of excessive sugar correction and, consequently, a reduction in time spent in hyperglycemia as well." (PMID 38836230, 2024). "Only one in ten infants developed hyperglycaemia treated by insulin treatment during the BTM course, which is close to that we reported in a previous study that included very premature infants treated by BTM (11%)." (PMID 39604779, 2024). "RA can reduce hyperglycemia and ameliorate insulin sensitivity by decreasing PEPCK expression and increasing GLUT4 expression for glucose uptake." (PMID 38903985, 2024). "DM is an endocrine and metabolic disease defined by hyperglycemia brought on by insufficient insulin synthesis or dysfunctional insulin." (PMID 39599599, 2024). "al., who found that nifedipine induced hyperglycemia through a postulated inhibition mechanism of baseline and glucose-induced insulin production." (PMID 39204160, 2024). "The placenta secretes both leptin and adiponectin into the maternal circulation, the former being increased in obese pregnancies and contributing to impaired maternal glucose-stimulated insulin release (GSIS), adding to the risk of GDM and fetal hyperglycemia." (PMID 39377073, 2024). "Diabetic patients have adapted to chronic hyperglycemia and have resistance to lowering glucose with the same insulin dose due to insulin resistance and beta-cell secretory defects." (PMID 38330019, 2024). "A third debate is regarding the use non -nutritive sweeteners instead of sucrose to minimize insulin doses and decrease hyperglycemia and complications." (PMID 39227957, 2024). "A US study with 222 participants showed that 66% of the respondents were awakened at least once a week by a hyperglycemia warning, and most patients benefited from the alarm by taking an extra correction bolus of insulin to improve glycemic control." (PMID 38304693, 2024). "The incidence of severe hyperglycaemia was significantly lower in patients treated with imatinib, while insulin production and central insulin sensitivity were unaffected." (PMID 38424569, 2024). "In fact, NGR1 augmented both phases of glucose-stimulated insulin secretion indicating that NGR1 also acts by potentiating glucose-induced insulin secretion to reduce postprandial hyperglycemia similar to GLP-1 agonists, well-known antidiabetic class of drugs." (PMID 39399466, 2024). "Hyperglycemia arises from CCBs inhibiting calcium-mediated insulin secretion from pancreatic Islet cells." (PMID 39238719, 2024). "The administration of the HSE extract substantially reduced hyperglycemia and increased insulin production, with concurrent improvements in body weight and hydration." (PMID 38929670, 2024). "IR refers to a condition where peripheral cells, such as the liver, adipose tissue, and skeletal muscle, fail to respond normally to insulin, resulting in hyperglycemia and hypertriglyceridemia." (PMID 39765954, 2024). "T2DM is documented as a metabolic disorder, attributed to abnormal insulin production and/or peripheral resistance to the action of insulin, advancing the development of hyperglycaemia." (PMID 38731811, 2024). "Other studies have proposed that prolonged hyperglycemia and disrupted insulin signaling hinder autophagic flux, resulting in the accumulation of dysfunctional cellular components that can contribute to β-cell dysfunction." (PMID 38971910, 2024). "Hybrid closed-loop (HCL) technology integrates a CGM with an insulin pump and an algorithm to automatically adjust basal insulin in response to sensor glucose changes and predictively adjust insulin delivery to minimize hypoglycemia and hyperglycemia." (PMID 38215206, 2024). "If hyperglycemia does persist, it is usually possible to reduce or discontinue insulin whilst introducing oral hypoglycemic medication." (PMID 38674437, 2024).
Hyperglycemia (continued). "Hernández-Rodríguez and coworkers reported that the increase in fetal vaspin concentration in response to maternal hyperglycemia was related to improved fetal insulin utilization." (PMID 39795898, 2024). "Whereas hyperglycemia has long been thought to be the primary driver in the progression of diabetic complications, impaired insulin signaling is also suspected to contribute to the retinal pathology." (PMID 38952394, 2024). "Chronic hyperglycemia leads to glucose toxicity and worsening of impaired insulin secretion due to the overworking of pancreatic β-cells, which results in a decreased ability to secrete insulin." (PMID 38533089, 2024). "Daily treatment with insulin administrated subcutaneously in the STZ-diabetic rats showed a reduction in hyperglycemia (>250 mg/dL) to normalized values." (PMID 38794147, 2024). "The sequential administration of nicotinamide and STZ effectively replicates key aspects of T2DM, including β-cell dysfunction, insulin resistance, hyperglycemia, and dyslipidemia, resembling the progressive nature of the disease in humans." (PMID 39203819, 2024). "Hyperglycemia, insulin, and increased glucose levels in newborns also raise the chance of developing prematurity-related retinopathy." (PMID 38618439, 2024). "Two other important potential obstacles to optimal insulin treatment in T1D are the dawn phenomenon and the late-afternoon hyperglycemia." (PMID 38982528, 2024). "While anti-tumor medication helps to restrict tumor proliferation, it can simultaneously downregulate insulin-mediated glucose disposal to skeletal muscle and promote hyperglycemia/hyperinsulinemia." (PMID 38166036, 2024). "Of the subjects, 79 (66.4%), eight (6.7%), and 32 (26.8%) were under OHA, insulin, and both medications showing compliance to medication and a willingness to control hyperglycemia." (PMID 39224717, 2024). "DM is a metabolic chronic disorder characterized by long-term hyperglycemia due to impaired insulin secretion and/or defects in insulin action." (PMID 38515857, 2024). "Hyperglycemia is the most common on-target side effect of PI3K inhibitors because of the central role of PI3Kα in insulin signaling." (PMID 38992135, 2024). "Eventually, any compensations by beta-cells fail to meet the increasing insulin need, resulting in hyperglycemia and, finally, an insulin-dependent status." (PMID 36991252, 2024). "Now, it is well acknowledged that both T1DM and T2DM converge on impaired insulin secretion and uncontrolled hyperglycemia secondary to pancreatic β-cell dysfunctionality, ultimately necessitating insulin therapy." (PMID 38966213, 2024). "A recent study investigated glucose concentrations in response to hyperglucagonemia and also noted transient hyperglycemia in an insulin-clamped canine model." (PMID 38814331, 2024). "Studies in rabbits highlight that hyperglycemia impairs phagocytosis in both neutrophils and monocytes, and insulin administration reverses this dysfunction." (PMID 38787165, 2024). "Insulin resistance in trophoblastic cells, exacerbated by Klotho overexpression, leads to maternal hyperglycemia and disrupted nutrient transfer, contributing to fetal overgrowth (macrosomia) and increased risk of delivery complications." (PMID 39519193, 2024). "Pro-inflammatory cytokines decrease insulin secretion in a clonal pancreatic β-cell line, explaining the classical features of metabolic syndrome, including central adiposity, hyperglycemia, and dyslipidemia seen in-vivo models." (PMID 38416754, 2024). "In patients with GDM, impaired skeletal muscle glucose uptake due to defects in insulin signal transduction leads to maternal hyperglycemia." (PMID 39429784, 2024). "Real cases of hyperglycemia require medical intervention, and the patient should be given an insulin injection." (PMID 38344477, 2024). "The major clinical manifestation is chronic hyperglycemia which results from impaired insulin secretion or/and impaired insulin action." (PMID 38381379, 2024).
Hyperglycemia (continued). "Based on the results discussed in this review, heavy metals, especially cadmium, induce oxidative stress, pancreatic β-cell dysfunction, hyperglycemia, and disrupt insulin secretion, which induces and exacerbates T1D and T2D." (PMID 39415790, 2024). "Hyperglycemia can result from decreased insulin secretion, diminished glucose utilization, and increased glucose production, underscoring the intimate connection between hyperglycemia and glucose metabolism." (PMID 38918764, 2024). "SGLT-2 inhibitors improve glycemic control by reducing blood glucose levels and enhancing insulin sensitivity, thereby mitigating the detrimental effects of hyperglycemia on neuronal cells." (PMID 39728750, 2024). "When mice with STZ-T1D were engrafted with those engineered HF-MSCs, the cells expressed and released a dose of human insulin, dramatically reversed hyperglycemia, and significantly reduced death rate." (PMID 39468609, 2024). "According to the literature, perioperative hyperglycemia is associated with the development of PTDM, mainly when treatment with insulin is required." (PMID 38352660, 2024). "In T1D and T2D, hyperglycemia occurs because plasma insulin levels cannot meet the organism’s needs." (PMID 39120275, 2024). "Regarding surface loading, the binding of glucose derivative-modified insulin on RBCs was reversible in hyperglycemia and prolonged the therapeutic effects of insulin in diabetic mice." (PMID 38270470, 2024). "Hyperglycaemia distorts the insulin/insulin receptor/phosphatidylinositol 3 kinases/GLUT signalling pathway, which results in hyperinsulinaemia and the activation of many inflammatory factors, such as cytokines and adhesion factors." (PMID 39456664, 2024). "The surgical stress response leads to the release of catabolic hormones and the inhibition of insulin function, resulting in the development of hyperglycemia." (PMID 39095723, 2024). "Hyperglycaemia was the reason for the insulin pump usage and refractory hypotension for intravenous lipid emulsion application." (PMID 38399472, 2024). "The administration of B. uniformis to obese mice improved glucose tolerance and insulin secretion, restored the caloric intake suppression after an oral glucose challenge, and reduced hyperglycemia." (PMID 38845049, 2024). "IR is characterized by a decreased sensitivity and responsiveness to insulin, leading to impaired glucose utilization and subsequent metabolic abnormalities such as hyperglycemia." (PMID 39906035, 2024). "It is characterised by hyperglycemia or surging blood glucose levels due to anomalies in insulin production or insulin action." (PMID 39345858, 2024). "Larvae developed hyperglycaemia, and the hyperinsulinaemic state was confirmed as altered insulin signalling resulted." (PMID 38279951, 2024). "This mismatch led to suboptimal glycemic control, including postprandial hyperglycemia and delayed hypoglycemia as insulin activity persisted beyond the period of glucose absorption." (PMID 39766270, 2024). "Using Alx3-deficient mice on a hybrid FVBxC57BL/6J background we found altered glucose homeostasis due to dysfunctional pancreatic islets resulting in mild hyperglycemia, glucose intolerance and impaired insulin secretion." (PMID 39129011, 2024). "DM is mainly characterized by hyperglycemia due to abnormalities in insulin secretion or insulin action." (PMID 39458514, 2024). "In β-cells Met−/− mice, a mild hyperglycemia and loss of acute-phase insulin response to glucose highlight the importance of HGF-Met signaling for normal glucose-dependent insulin secretion and homeostasis." (PMID 38654922, 2024). "Intensive use of exogenous insulin has been shown to slow the progression of hyperglycemia-related complications in patients with T1D, improving quality of life and reducing associated costs; however, it increases the risk of hypoglycemia." (PMID 38337523, 2024). "Current medical treatments for hyperglycemia include insulin administration and oral antidiabetic drugs." (PMID 39597869, 2024).
Hyperglycemia (continued). "By avoiding a peak in blood glucose levels 2 h postprandially and promoting a gradual rise in blood sugar, quinoa helps compensate for insufficient insulin secretion from islet beta cells or prevents postprandial hyperglycemia." (PMID 39430786, 2024). "Another resistance mechanism is the suppression of the insulin feedback loop, whereby systemic hyperglycemia and hyperinsulinemia induced by PI3K inhibition can reactivate the PAM pathway in cancer cells." (PMID 38839777, 2024). "Glucocorticoids directly increase hepatic insulin resistance and gluconeogenesis-related enzymes in the liver, leading to hyperglycemia." (PMID 39165284, 2024). "SARS-CoV-2, by binding and damaging islets, diminishes the ability of the pancreas to release insulin in response to the resultant hyperglycemia." (PMID 39099965, 2024). "The early signs of burn-related sepsis are increased fluid requirements, decreased urine output, confusion, feeding intolerance, diarrhea, hyperglycemia, increased insulin requirements and high fever (>39.0 °C)." (PMID 39599952, 2024). "Data will be helpful for both the patient and the healthcare professional in making informed decisions about administering insulin or making dietary choices to minimize the risks of hypoglycemia and hyperglycemia." (PMID 39590019, 2024). "On the one hand, insulin therapy limits the potential consequences of hyperglycemia including acute conditions such as acidosis or a hyperosmolar hyperglycemic state." (PMID 39407860, 2024). "Catechins and quercetin, present in Amaranthus, improved hyperglycemia and insulin sensitivity through the activation of AKT2 and AMPK, increasing the expression of GLUT4, AKT2, and AMPK alpha 2, whose levels are reduced under diabetic conditions." (PMID 39434897, 2024). "Adenosine monophosphate (AMP)–activated protein kinase (AMPK) functions to reduce hyperglycemia through insulin-independent pathways and protects beta-cells." (PMID 39885962, 2024). "GDM is characterized by the inability of pancreatic β-cells to adequately respond to the increased demand for insulin during pregnancy, resulting in various degrees of hyperglycemia." (PMID 38674907, 2024). "Because of insulin resistance, cells need more insulin for converting glucose into energy, which inevitably raises blood sugar levels and leads to hyperglycemia." (PMID 39771551, 2024). "The indirect effects of hypercortisolism include long-standing hyperglycaemia, which results in oxidative damage within the cell and insulin resistance." (PMID 39062179, 2024). "A small trial including 8 patients with T1D showed improved postprandial hyperglycemia despite 20% insulin dose reduction." (PMID 39906033, 2024). "The algorithm gives automated bolus insulin corrections to combat hyperglycemia, as well as building low-glucose protection." (PMID 39062288, 2024). "Key indicators of diabetes include hyperglycemia, varied levels of insulin resistance, and decreased insulin production." (PMID 39727640, 2024). "In order to avoid the occurrence of malignant hypoglycemia events, modified intensive insulin therapy for stress hyperglycemia is gradually accepted." (PMID 39009963, 2024). "It is a metabolic syndrome characterized by prolonged hyperglycemia due to defects in insulin secretion and action resulting in metabolic disorders of carbohydrates, fats and proteins." (PMID 38568081, 2024). "Hyperglycemia and high insulin levels drive de novo lipogenesis-hyperglycemia through ChREBP and hyperinsulinemia through SREBP1c." (PMID 39070477, 2024). "Hyperglycemia occurs in up to 80% of subjects on clinical trials for PI3K/AKT inhibitors since this pathway controls insulin sensitivity and glucose metabolism." (PMID 39099917, 2024). "Improved hyperglycemia reduced the oral hypoglycemic medication in two cases and decreased the frequency of insulin injections in two cases." (PMID 38525744, 2024).